HAUS6 (HAUS augmin like complex subunit 6)
Description:
Contributes to mitotic spindle assembly, maintenance of centrosome integrity and completion of cytokinesis as part of the HAUS augmin-like complex. Promotes the nucleation of microtubules from the spindle through recruitment of NEDD1 and gamma-tubulin.
Synonyms: DGT6; FAM29A; KIAA1574; FLJ20060
Tractability: PROTAC: ubiquitination databases record sites on it; its protein half-life has been measured.
Gene: Protein-coding gene on chromosome 9 (19,053,141 to 19,102,927, reverse strand). Ensembl gene ENSG00000147874.
Subcellular location: Cytoplasm, cytoskeleton; Cytoplasm, cytoskeleton, spindle; Cytoplasm, cytoskeleton, microtubule organizing center, centrosome
Subcellular location (Human Protein Atlas): Acrosome; Centriolar satellite; Cytosol; Connecting piece; Mid piece; Nuclear speckles; Principal piece
Pathways (Reactome):
Cell Cycle: AURKA Activation by TPX2; Loss of Nlp from mitotic centrosomes; Loss of proteins required for interphase microtubule organization from the centrosome; Recruitment of NuMA to mitotic centrosomes; Recruitment of mitotic centrosome proteins and complexes; Regulation of PLK1 Activity at G2/M Transition
Organelle biogenesis and maintenance: Anchoring of the basal body to the plasma membrane
Gene Ontology:
Molecular function: protein binding
Biological process: centrosome cycle; spindle assembly; regulation of microtubule nucleation
Cellular component: centrosome; HAUS complex; mitotic spindle microtubule; cytosol; cytoskeleton; spindle
Genetic constraint (gnomAD): Loss-of-function variants: 22 observed, 25.94 expected, observed/expected ratio (o/e) 0.85, 90% interval 0.61 to 1.21. The upper end of that interval is the gene's LOEUF score, 1.21, which puts it in group 5 of 6, group 1 being the genes least tolerant of losing a copy. Missense variants: 409 observed, 421.49 expected, observed/expected ratio (o/e) 0.97, 90% interval 0.89 to 1.05. Synonymous variants: 150 observed, 153.23 expected, observed/expected ratio (o/e) 0.98, 90% interval 0.86 to 1.12.
Homologues: Orthologues: chimpanzee HAUS6 (99% identical), macaque HAUS6 (95% identical), rabbit HAUS6 (79% identical), pig HAUS6 (78% identical), dog HAUS6 (77% identical), guinea pig HAUS6 (72% identical), rat Haus6 (66% identical), mouse Haus6 (64% identical), tropical clawed frog haus6 (36% identical), zebrafish haus6 (21% identical), Drosophila melanogaster dgt6 (12% identical).
Diseases named in the same sentence as HAUS6 in open-access papers:
HAUS6 is named in the same sentence as 11 diseases in open-access papers, as found by Europe PMC text mining. Sharing a sentence is not in itself a finding about the gene and the disease. The quoted sentences say what the papers report.
Type 2 Diabetes (2 papers, 2020 to 2023). "Ten VAT-specific candidate genes were associated with type 2 diabetes after Bonferroni correction, including five causal genes supported by SMR and co-localisation: PABPC4 (1p34.3); CCNE2 (8q22.1); HAUS6 (9p22.1); CWF19L1 (10q24.31); and CCDC92 (12q24.31)." (PMID 37540242, 2023). "The effects of two other causal genes, CCNE2 and HAUS6, on type 2 diabetes have not been validated in functional studies and will need to be investigated in future research." (PMID 37540242, 2023). "Besides, genetically elevated expression of CCNE2 on 8q22.1, HAUS6 on 9p22.1, CWF19L1 on 10q24.31, CCDC92 on 12q24.31 and DNAH10OS on 12q24.31 showed protective effects on type 2 diabetes risk." (PMID 37540242, 2023). "According to the analysis of bulk RNA-seq data, three significantly differentially expressed TWAS-identified genes were observed when comparing individuals with type 2 diabetes and non-diabetic individuals with morbid obesity: PABPC4 (p=0.004); HAUS6 (p=0.011); and DNLZ (p=0.013)." (PMID 37540242, 2023).
Allergy (1 paper, 2017). An allergy is an immune response or reaction to substances that are usually not harmful. "However, nonsynonymous mutations were identified in the coding sequences of Cer1, Ttc39b, Ccdc171, Cntln, Adamtsl1, Haus6, Gm12551, and Dennd4c, but these genes do not have any prior documented associations with allergy, IgE, or asthma." (PMID 28696925, 2017).
endometrial carcinoma (1 paper, 2024). A malignant tumor arising from the epithelium that lines the cavity of the uterine body. "Therefore, we further determined the expression levels of CDC6, EGFR, and HAUS6 during PCOS carcinomatosis to endometrial carcinoma." (PMID 39684684, 2024).
glioma (1 paper, 2023). A benign or malignant brain and spinal cord tumor that arises from glial cells (astrocytes, oligodendrocytes, ependymal cells). "Low expression of HAUS4 and HAUS6 and high expression of HAUS1, HAUS3, HAUS5, HAUS7, HAUS8 may be risk factors for poor prognosis in glioma patients." (PMID 37161065, 2023). "The research found that expression levels of the Augmin family genes HAUS1, HAUS3, HAUS4, HAUS5, HAUS6, HAUS7, and HAUS8 was all related with survival rates of glioma patients." (PMID 37161065, 2023).
Hypoglycemia (1 paper, 2020). A decreased concentration of glucose in the blood. "While HAUS6 and its nearby genes RRAGA and PLIN2 have various cancers (including PrCa) as associated diseases in Open Targets Genetics, one or more of them are related to metabolism phenotype, abnormal gluconeogenesis and hypoglycemia in mice." (PMID 33290408, 2020).
cancer (6 papers, 2019 to 2025). A tumor composed of atypical neoplastic, often pleomorphic cells that invade other tissues. "However, the biological function of HAUS6 in most malignant neoplasms (including CRC) remain largely unknown." (PMID 35096810, 2021). "These included multitrait colocalization at 6 loci with a consistent direction of effect between CAD and cancer (ABO, PGAP3, ANGPTL4, SREBF1, HAUS6, and SYNJ2BP) and 7 with an opposing direction (CDKN1A, RGS19, CALCRL, SF3A3, LAMC1, MYO9B, and MIA3)." (PMID 40874306, 2025). "However, the role of HAUS6 in cancer has never been evaluated to our knowledge." (PMID 35096810, 2021).
tumor (3 papers, 2021 to 2023). "Series of functional study show that knockdown of the spindle assembly factor HAUS6 suppressed tumor growth in vivo and in vitro by inhibiting cell viability, survival and cell cycle progression." (PMID 35096810, 2021). "HAUS6 knockdown strongly reduced tumor volume and decreased fluorescence of tumor cells in nude mice injected with GFP-expressing CRC cells." (PMID 35096810, 2021). "HAUS6 knockdown suppressed tumor growth by inhibiting cell viability and survival as well as by arresting cells in G0/G1, which were enhanced after combination of 5-FU treatment." (PMID 35096810, 2021). "Immunohistochemistry of the excised tumors showed that Ki-67 protein expression was decreased in HAUS6 knockdown cells, suggesting that HAUS6 knockdown suppresses CRC tumor growth by inhibiting cell proliferation." (PMID 35096810, 2021).
HAUS6 also shares sentences with these, for which no sentence is quoted: colorectal cancer (3 papers); asthma (1); morbid obesity (1); prostate carcinoma (1).